EGFR (epidermal growth factor receptor)
Diseases named in the same sentence as EGFR in open-access papers (continued):
Sharing a sentence is not in itself a finding about the gene and the disease.
colorectal cancer (continued). "Approximately 30–40% of colorectal cancers (CRC) harbor activating mutations in Kirsten Ras (KRAS) proto-oncogene, which encodes for a GTPase transductor protein downstream of epidermal growth factor receptor (EGFR) as part of the RAS/RAF/MAPK pathway." (PMID 34108518, 2021). "EGFR overexpression has been observed in 43.9–97% of colorectal cancer patients based on IHC analysis." (PMID 36405499, 2021). "In this study, we focused on the development of a bispecific antibody approach to target NK cells to EGFR expressing colorectal cancer." (PMID 34771609, 2021). "More importantly, the new insights into the activation of EGFR/Akt/GSK3β signaling axis medicated by PRMT5 provide much new information for the mechanisms of the carcinogenic effect of PRMT5 in human colorectal cancer." (PMID 33495409, 2021). "Consistently, YAP downregulation-induced chemosensitivity to EGFR-TKIs was also detected in ovarian cancer and colorectal cancer cells expressing EGFR." (PMID 33467099, 2021). "Currently, four monoclonal antibodies (mAb) targeting the extracellular domain of EGFR are approved for clinical use against various cancers of epithelial origin (e.g., colorectal cancer (CRC) and head and neck cancer)." (PMID 34771609, 2021). "Relieving the negative feedback from S6K on IRS was previously shown to sensitize colorectal cancer cells to EGFR inhibition." (PMID 34191793, 2021). "Determining the status of EGFR and KRAS mutations is crucial for guiding treatment in NSCLC patients receiving EGFR tyrosine kinase inhibitors and colorectal cancer patients treated with anti-EGFR therapy respectively." (PMID 34803167, 2021). "Genetic alterations of EGFR are found in several tumors, including glioblastoma, lung, breast, gastric, and colorectal cancers." (PMID 33918836, 2021). "In contrast to melanomas, BRAF-driven colorectal cancers require EGFR inhibition to prevent an activation of the compensatory signaling cascade, and are usually treated by combined administration of anti-EGFR antibodies and antagonists of mutated BRAF." (PMID 34681592, 2021). "EGFR and Src, by way of its enhancement of EGFR signaling are key pathways in the development of colorectal cancer, along with several other cancers." (PMID 34926717, 2021). "Cetuximab is an effective antibody to treat colorectal cancer (CRC) by targeting the epidermal growth factor receptor (EGFR)." (PMID 34447749, 2021). "We found that c-MET expression is higher (p = 1.24e-07) while EGFR expression is lower (p = 4.67e-04) in colorectal cancer cohorts compared to adjacent normal cohorts." (PMID 34512327, 2021). "It looks like a novel metastatic colorectal cancer marker whose expression level permits for the selection of patients with wild-type KRAS cancer who more possibly respond to anti-EGFR treatment." (PMID 34350290, 2021). "Anoikis induction through the EGFR/Akt pathway in HCT116 colorectal cancer cells was confirmed by Western blotting." (PMID 34094906, 2021). "Enhancement of NK cell activation by the bispecific VHH was also observed when NK cells of colorectal cancer (CRC) patients were co-cultured with EGFR expressing tumor cells." (PMID 34771609, 2021). "A study on colorectal cancer has also demonstrated that 8-gingerol inhibits epidermal growth factor receptor (EGFR) signaling." (PMID 33706784, 2021). "But previous study showed the superiority in the response rate of advanced colorectal cancer treated with FOLOX plus anti-EGFR antibody compared to FOLFOX." (PMID 33489709, 2021). "For example, anti-EGFR therapy is excluded in patients with KRAS mutant colorectal cancer due to receptor tyrosine kinase (RTK)-independent activation of mutant KRAS." (PMID 34680229, 2021). "We also evaluated the clinical significance of CD73 expression in colorectal cancer patients receiving MAPKi (anti‐EGFR, cetuximab) and demonstrated a significantly worse outcome associated with high CD73 expression." (PMID 34165921, 2021).
colorectal cancer (continued). "This is well documented in colorectal cancer, where RAS mutations are used to estimate the potential success of anti-EGFR treatment." (PMID 33920536, 2021). "Integrated transcriptional profiling and genomic analyses reveal that ribophorin II is a promising biomarker in colorectal cancer and promotes colorectal cancer proliferation via regulating the glycosylation status of EGFR." (PMID 34512323, 2021). "Of note, in the colorectal cancer cells, these responses seemed limited to cells that were sensitive to lapatinib, and therefore dependent on EGFR signalling." (PMID 35582302, 2021). "We aimed to verify the EGFR/Akt pathway-mediated anoikis-inducing effects of SAE in vitro in HCT116 colorectal cancer cells." (PMID 34094906, 2021). "Epidermal growth factor receptor (EGFR) inhibition has proven to be an effective therapy in KRAS wild-type patients with advanced colorectal cancer." (PMID 34956889, 2021). "Nearly 80% of colorectal tumors overexpress EGFR, and hence EGFR is one of the major targets in colorectal cancer (CRC)." (PMID 33670650, 2021). "More importantly, our results also uncover that PRMT5 promotes EMT in colorectal cancer cells via EGFR/Akt/GSK3β signaling axis." (PMID 33495409, 2021). "Herein, we used a multiomics data analysis to evaluate the predictive and prognostic roles of genetic and epigenetic modulation of c-MET (hepatocyte growth factor receptor)/epidermal growth factor receptor (EGFR) in colorectal cancer (CRC)." (PMID 34512327, 2021). "This study showed that SAE, by containing β-sitosterol with proven anticancer effects, induces anoikis through the EGFR/Akt pathway in HCT116 colorectal cancer cells both in vitro and in vivo." (PMID 34094906, 2021). "Panitumumab is a recombinant human IgG2 monoclonal antibody that binds specifically to EGFR and has demonstrated clinical efficacy in colorectal cancer." (PMID 34956889, 2021). "Morphine promotes tumorigenesis and cetuximab resistance via EGFR signaling activation in human colorectal cancer." (PMID 34642262, 2021). "Treatment resistance patterns in colorectal cancer, especially to epidermal growth factor receptor (EGFR) inhibition, have been extensively investigated." (PMID 35127745, 2021). "For example, the anti-EGFR cetuximab and panitumumab are used in clinic to treat head and neck cancer and colorectal cancer." (PMID 34359650, 2021). "Clinical management of skin-toxicity associated with the use of anti-Epidermal Growth Factor Receptor (EGFR) antibodies to treat colorectal cancer maintains quality of life of patients with colorectal cancer." (PMID 34593037, 2021). "A considerable fraction of EGFR mutations, particularly for UGI, breast, and colorectal cancer, were subclonal variants that were mainly located at the extracellular domain of the coding protein, probably induced by anti-HER2 therapy." (PMID 33397889, 2021). "In such a frame, we detail the interaction of the EphA2 and EGFR pathway in solid tumors, including colorectal cancer." (PMID 33572284, 2021). "When combined with EGFR pathway inhibitors, RAS-mutated colorectal cancer cells can be sensitized again, which provides a new choice for the clinical treatment of colorectal cancer patients." (PMID 34020369, 2021). "In colorectal cancer (CRC), examination of molecular alterations indicated that mutations in KRAS, which is downstream from EGFR in the RAS-MEK-ERK signaling pathway, interfered with this therapy." (PMID 33920536, 2021). "In conclusion, this study showed that SAE containing physiological compounds such as β-sitosterol, which have been shown to have anticancer effects in colorectal cancer cells, induces anoikis through the EGFR/Akt pathway." (PMID 34094906, 2021).
colorectal cancer (continued). "A variety of targeted drugs, such as bevacizumab (targeting VEGF), cetuximab and erlotinib (targeting EGFR), have been clinically applied in the treatment of colorectal cancer." (PMID 33726765, 2021). "For example, EGFR signalling was found to be the dominant mechanism of resistance in one study on colorectal cancer." (PMID 34200676, 2021). "In general, the significance of anti-epidermal growth factor receptor (EGFR) antibodies has been proven in wild-type RAS left-sided colorectal cancer." (PMID 34425776, 2021). "For example, ASA was shown to normalize EGFR expression and inhibit EGFR signaling both in human colorectal cancer (CRC) cells and ovarian cancer cells in vitro." (PMID 34073241, 2021). "Along those lines, it has been demonstrated that colorectal cancer cells resistant to the EGFR blockade express TGF-α that sustains EGFR/ERK pathways and thus protects their sensitive counterparts from EGFR inhibitors." (PMID 33803675, 2021). "loaded 5-FU on Au nanoparticles coated with anti-EGFR (EGF receptor) antibodies to treat colorectal cancer." (PMID 35083147, 2021). "Liquid biopsy-guided genomic studies performed in colorectal cancer have demonstrated a significant increase in RAS mutant clones in plasma at the onset of secondary resistance to anti-EGFR therapy." (PMID 34943432, 2021). "Compared to N-MrNV, the chimeric R-MrNV and E-MrNV carrying the exposed GE-11 peptide showed a significantly enhanced binding and internalization abilities that were specific towards EGFR expression in colorectal cancer cells (SW480)." (PMID 34400669, 2021). "Although the EGFR and K-RAS mutations are mutually exclusive in clinical observations of NSCLC and colorectal cancer, they have been found to co-exist in PDAC despite EGFR mutation only accounting for less than 3% of PDAC." (PMID 34360896, 2021). "Inhibition of EGFR signaling has been shown to reduce uncontrolled cell growth, and EGFR targeted pharmaceuticals are used in the treatment of colorectal cancer." (PMID 33515553, 2021). "The mutation of KRAS is related with the resistance to EGFR-targeted therapeutics, and the loss of the tumor suppressor PTEN implies more aggressive tumorigenesis from these patients with advanced colorectal cancer." (PMID 35003350, 2021). "Using a combination of in vitro and in vivo assays, we demonstrate that Tspan6 functions as a tumor suppressor in colorectal cancer (CRC) by attenuating the epidermal growth factor receptor (EGFR)–based signaling axis." (PMID 34521767, 2021). "Lidocaine enhances apoptosis and reduces proliferation by inducing miR-520a-3p expression to inhibit EGFR in colorectal cancer cells." (PMID 34122108, 2021). "This suggests that the issue of KRAS activation needs to be tackled before EGFR inhibitors will be fully effective in more colorectal cancer cases." (PMID 33801965, 2021). "RAS is the most common mutated gene in colorectal cancer (CRC), and its occurrence is associated with primary and acquired resistance to anti-epidermal growth factor receptor (EGFR) blockade." (PMID 34745987, 2021). "Approximately 10% of colorectal cancers harbor native mutations in PTPRS, and inactivation of PTPRS promotes ERK and AKT activation, resulting in enhanced RAS and EGFR activity in colorectal cancer." (PMID 34805171, 2021). "Wang and colleagues have recently shown a synergistic inhibition of colorectal cancer (CRC) cell growth through simultaneous inhibition of the EGFR and CDK4/6 pathways." (PMID 33809148, 2021). "If the response of duodenal adenocarcinoma was similar to that of colorectal cancer, angiogenesis inhibitors would be better than EGFR inhibitors for the treatment of duodenal adenocarcinoma with KRAS mutation." (PMID 34797780, 2021).
colorectal cancer (continued). "ILF3 has been reported to function as a critical regulator for the serine-glycine one-carbon (SGOC) pathway in colorectal cancer (CRC) via EGFR-ERK axis followed by E3 ligase speckle-type POZ protein (SPOP)-mediated poly-ubiquitination and degradation of ILF3." (PMID 34568427, 2021). "For example, colorectal cancer patients with wild type proto-oncogene KRAS or BRAF benefit often from treatment with monoclonal antibodies targeting the epidermal growth factor receptor (EGFR)." (PMID 34805167, 2021). "For instance, chemotherapy resistance in colorectal cancer has been attributed to EGFR phosphorylation and activation of the downstream pathway through growth factor binding ability of heparan sulfate chains existing on shed SDC-1." (PMID 33562126, 2021). "There exists an extensive crosstalk between Wnt- and EGFR-dependent signaling pathways in colorectal cancer." (PMID 34521767, 2021). "It is notable that studies on colorectal cancer demonstrated the feasibility of adding anti-EGFR therapy to BRAF inhibitors in order to prevent feedback activation of EGFR receptor." (PMID 34681592, 2021). "This antibody binds to the EGFR, which is overexpressed in several types of cancer such as colorectal carcinoma." (PMID 34452282, 2021). "The EGFR pathway is known to be overexpressed in 60–80% of colorectal cancer, which drives its oncogenicity." (PMID 32620824, 2020). "For example, the presence of a KRAS mutation has long been recognized as a marker of resistance to EGFR inhibitors (EGFRi) for patients with colorectal cancer (CRC)." (PMID 33153459, 2020). "Only studies of EGFR (epidermal growth factor receptor) mutated NSCLC patients receiving TKIs and those with colorectal cancer receiving oral chemotherapy showed a significant correlation between GAS and poor survival." (PMID 32325628, 2020). "EGFR was upregulated by FOXK2 in colorectal cancer to enhance the metastasis of colorectal cancer cells." (PMID 32231464, 2020). "In the well-studied example of colorectal cancer, monotherapy targeting the epidermal growth factor receptor (EGFR) inevitably resulted in the expansion of KRAS mutant subpopulations that drive patient relapse." (PMID 32898185, 2020). "The dual epitope targeting anti-EGFR antibody combination Sym004, which has shown therapeutic efficacy in colorectal cancer and is currently being trialled in randomised studies, was used in this work." (PMID 31959764, 2020). "EGFR inhibition with cetuximab in colorectal cancer underwent a concurrent transformation from benefit across the patient population, to those without KRAS mutations, and now even more limited to those with left-sided pan-RAS wildtype tumors." (PMID 33364187, 2020). "Macrophage Migration Inhibitory Factor (MIF) has been identified as a molecular determinant of the anti-EGFR cetuximab resistance in human colorectal cancer cells." (PMID 32245422, 2020). "The long-term efficacy of the Epidermal Growth Factor Receptor (EGFR)-targeted antibody cetuximab in advanced colorectal cancer (CRC) patients is limited by the emergence of drug-resistant (persister) cells." (PMID 32183295, 2020). "KRAS, which was involved in NCCN guidelines for colorectal cancer in 2008 for the first time, has proven to be a key biomarker in applying EGFR-targeted therapies." (PMID 33628729, 2020). "Cetuximab is a target therapy for colorectal cancer that works in the EGFR extracellular domain by inhibiting MAPK pathway." (PMID 32765634, 2020). "Our results also indicated that IRE1α-XBP1s activation was correlated with EGFR expression in colorectal cancer." (PMID 32489465, 2020).
colorectal cancer (continued). "Among the cancer pathways, epidermal growth factor receptor (EGFR) plays a crucial role in the carcinogenesis, invasion and metastasis of colorectal cancer." (PMID 32329374, 2020). "Cetuximab is a target therapy for colorectal cancer that works in the EGFR extracellular domain by inhibition of K-Ras." (PMID 32765634, 2020). "MiR-141-3p acts as a tumor-suppressor gene in colorectal cancer and enhances the sensitivity of colorectal cancer cells to cetuximab by inhibiting EGFR." (PMID 33490103, 2020). "The present study has produced and characterized AuNPs smaller than 20 nm, which were capable of carrying 5-FU to colorectal cancer cells overexpressing EGFR." (PMID 31947551, 2020). "The already reported positive correlation between EGFR and Matrix-metalloprotease-7 (MMP-7) seems to play a role in colorectal cancer, and EGFR-mediated MMP-7 up-regulation promotes epithelial-mesenchymal transition during ovarian endometriosis progression." (PMID 32604857, 2020). "One example of this is the high-quality retrospective analysis of randomized phase three clinical trial data sets, which led to the routine clinical use of KRAS as a biomarker for response to anti-EGFR therapies in colorectal cancer." (PMID 33442473, 2020). "A recent study has shown the regulatory mechanism of EGFR/ERK/AKT signaling in colorectal cancer cell growth and migration." (PMID 33335643, 2020). "The expression of EGFR in patients with oral cancer is elevated compared with that in patients with other cancer, such as colorectal cancer or bladder cancer." (PMID 32878053, 2020). "Although the advent of anti-EGF receptor (EGFR)-targeted therapies has significantly improved patients’ prognosis, effective treatment of advanced colorectal cancer is still an unmet need." (PMID 32244500, 2020). "8RAS (KRAS/NRAS) gene mutations are detected in approximately 50% of patients with unresectable colorectal cancer, and it was reported that the efficacy of anti-EGFR antibody therapy (CET, PANI) cannot be expected for patients with these mutations." (PMID 31203527, 2020). "EGFR antagonists (e.g., gefitinib, lapatinib, erlotinib) have been used in a variety of cancers, including pancreatic, small cell lung, and colorectal cancer." (PMID 32536817, 2020). "BRAFV600E melanomas, which have low expression of EGFR, are treatable with RAF inhibitors (e.g., vemurafenib); however, BRAFV600E colorectal cancers adapt to RAF inhibitors through compensatory activation of the EGFR and MAPK signaling pathways." (PMID 32033280, 2020). "Numerous factors can induce EMT in tumor cells including EGF, which initiates EMT in colorectal cancer cells through the EGF/EGFR signaling pathway, thereby facilitating invasion and metastasis." (PMID 32148496, 2020). "In order to confirm the clinical significance of the EGFR gene expression, we investigated its prognostic impact in an independent series of colorectal cancer patients from the public GEO database (n = 32)." (PMID 32170146, 2020). "First, we investigated the presence of a BRAFV600E mutation, which is known to be reliably predictive of resistance to the EGFR inhibitor cetuximab in colorectal cancer." (PMID 33127883, 2020). "Due to Abigail’s high expression of EGFR, her oncologist recommended Abigail for her terminal head and neck cancer to try an investigational EGFR-targeted drug, C222 (Erbitux), which was then undergoing clinical trial for the treatment of colorectal cancer." (PMID 32576276, 2020). "A correlation and adverse prognostic synergy between PODXL and the epidermal growth factor receptor (EGFR) has been observed in colorectal cancer." (PMID 32587323, 2020). "For instance, osimertinib, an EGFR inhibitor, was reported to work modestly in colorectal cancer due to induction of protective autophagy mediated by the MCT1/LKB1/AMPK axis." (PMID 32565796, 2020). "Previous work has shown that high expression of PODXL and EGFR impair survival in colorectal cancer in a synergistic way25." (PMID 32587323, 2020).